RBCK1 (RANBP2-type and C3HC4-type zinc finger containing 1)
Diseases named in the same sentence as RBCK1 in open-access papers (continued):
Sharing a sentence is not in itself a finding about the gene and the disease.
ovarian carcinoma (3 papers, 2020 to 2024). A malignant neoplasm originating from the surface ovarian epithelium. "Consistently, RBCK1 downregulation induced apoptosis and curtailed proliferative and migratory phenotypes in ovarian cancer cells." (PMID 38214606, 2024). "In the combined analysis of CLIP-seq, RIP-seq and RNA-seq data, we identified multiple potential direct binding targets (BCL2L12, RBCK1, E2F4, and CDK16) that may involve in BUD31-mediated ovarian cancer cell survival and proliferation." (PMID 36271053, 2022).
Parkinson disease (3 papers, 2012 to 2023). A progressive degenerative disorder of the central nervous system characterized by loss of dopamine producing neurons in the substantia nigra and the presence of Lewy bodies in the substantia nigra and locus coeruleus. "A second typical example is the convergent similarity of the Parkinson disease-related E3 parkin and another protein of the RBR family, called RBCK1 (a." (PMID 23185523, 2012).
polyglucosan body myopathy (3 papers, 2018 to 2020). "A subset of patients with polyglucosan body myopathy was found to have underlying mutations in the RBCK1 gene." (PMID 29260357, 2018). "Similarly, we also analyzed CD4+ T‐cells from a recently described female patient suffering from polyglucosan body myopathy (PBM) due to a mutation in the RBCK‐1 gene." (PMID 32319705, 2020). "This notably broadens the genotype–phenotype correlation of RBCK1-related polyglucosan body myopathy." (PMID 29260357, 2018).
breast tumors (2 papers, 2018 to 2021). "Correlation of ERalpha, RBCK1, RNF31 and SHARPIN mRNA expression levels in breast tumors." (PMID 29763465, 2018). "We compared RNF31, RBCK1 and SHARPIN mRNA and protein expression in a subset of breast tumors." (PMID 29763465, 2018).
Lafora disease (2 papers, 2017 to 2022). Lafora disease (LD) is a rare, inherited, severe, progressive myoclonic epilepsy characterized by myoclonus and/or generalized seizures, visual hallucinations (partial occipital seizures), and progressive neurological decline. "This type of storage in muscle is not unique for glycogenin-1 deficiency but is also found in deficiency of branching enzyme, phosphofructokinase and RBCK1 and in Lafora disease among others." (PMID 27718144, 2017).
pancreatic cancer (2 papers, 2022 to 2024). "Similarly, SRY-box transcription factor 13 (SOX13) and RANBP2-type and C3HC4-type zinc finger containing 1 (RBCK1) enhance resistance to ferroptosis in gastric and pancreatic cancers by boosting mitochondrial respiration." (PMID 39624080, 2024).
Sepsis (2 papers, 2018 to 2023). Sepsis is defined as life-threatening organ dysfunction caused by a dysregulated host response to infection. "Mutation of RBCK1 in M69 is associated with recurrent episodes of sepsis in children and causes death." (PMID 38071387, 2023).
thymoma (2 papers, 2021 to 2024). A neoplasm arising from the epithelial cells of the thymus. "Although RBCK1 expression was positively correlated with most cancer types, its expression had a significant negative association with immune checkpoints in thymoma samples." (PMID 34795663, 2021).
triple-negative breast carcinoma (2 papers, 2022 to 2024). An invasive breast carcinoma which is negative for expression of estrogen receptor (ER), progesterone receptor (PR), and human epidermal growth factor receptor 2 (HER2). "In contrast, ectopically expressed RBCK1 restricts the progression of triple-negative breast cancer (TNBC) in vitro and in vivo, whereas RBCK1 depletion stimulates the invasive capacity of TNBC cells." (PMID 38214606, 2024).
clear cell renal cell carcinoma (1 paper, 2025). "A conceptual parallel exists where RBCK1 promotes resistance to the tyrosine kinase inhibitor sunitinib in clear cell renal cell carcinoma, further validating its potential as a treatment-refractory biomarker." (PMID 41031125, 2025).
Cognitive impairment (1 paper, 2021). Abnormal cognition is characterized by deficits in thinking, reasoning, or remembering. "We describe a case of PGBM1 caused by a novel RBCK1 gene homozygous missense mutation presenting as skeletal myopathy with cerebral white matter changes and cognitive impairment that may be associated with the disease." (PMID 33413275, 2021). "This case from China with a novel homozygous missense mutation in RBCK1 extends the phenotypic spectrum and geographical distribution of PGBM 1, which may cause cerebral white matter changes and cognitive impairment." (PMID 33413275, 2021).
metabolism (1 paper, 2019). "To test the effects of RBCK1 depletion influence on metabolism disorder, we conducted glucose assay using two RCC cell lines." (PMID 30874541, 2019).
renal carcinoma (1 paper, 2019). A carcinoma arising from the epithelium of the renal parenchyma or the renal pelvis. "Through analysis of the renal cancer survival data, we revealed that patients with high expression of RBCK1 tended to achieve a shorter overall survival time, indicating that RBCK1 expression correlated with poor prognosis in RCC patients." (PMID 30874541, 2019). "Patients with high RBCK1 expression tended to have advanced TNM stage renal cancer (P = .004) and higher Fuhrman grade (P < .001), indicating that RBCK1 may be useful in predicting the staging of renal cancer." (PMID 30874541, 2019). "Subsequently, we performed RBCK1 depletion experiments in RCC cells that severely affected the in vivo and in vitro proliferation of renal cancer cells." (PMID 30874541, 2019).
tumor (20 papers, 2018 to 2025). "The study found that RBCK1 mutated in all 19 cancers, with the frequency of variation exceeding 5% in 15 tumor types, 10% in 11, 15% in 4, 20% in 2, and >25% in COAD." (PMID 38214606, 2024). "Results show that RBCK1 gene mutation is closely related to tumor prognosis (P < 0.05)." (PMID 38214606, 2024). "Furthermore, our results indicating an inverse association between RBCK1 mRNA expression and lymph node involvement are in agreement with a previous study, suggesting a less aggressive tumor phenotype when RBCK1 is highly expressed." (PMID 29763465, 2018). "We speculate that high RBCK1 expression might affect macrophage activities and drive the polarization of macrophages to M2 phenotype and eventual differentiation into tumor-associated macrophages (TAMs), which are critical players in the invasive, metastatic, and angiogenic potential of tumors." (PMID 38214606, 2024). "Based on the differential expression of RBCK1, we assessed the effect of RBCK1 in different tumor-infiltrating immune cells in HCC." (PMID 38214606, 2024). "RBCK1, a gene related to IFN-γ signaling, is associated with tumor immune infiltration as well as immunotherapy." (PMID 37231081, 2023). "In any case, our study identified a new regulator of the HIF1α signaling pathway, RBCK1, which can modulate tumor progression in ER-positive breast cancer cells by modulating this pathway, providing a new target for the treatment of ER-positive breast cancer." (PMID 36473847, 2022). "QRT-PCR showed that the expression of AIM2, CASP4, GSDMB, NOD2, and RBCK1 was significantly upregulated in tumor samples." (PMID 36248876, 2022). "Then, we investigated the expression levels of AIM2, CASP4, GSDMB, NOD2, and RBCK1 in cell lines and tumor tissues by qRT-PCR, IHC." (PMID 36248876, 2022). "We observed higher expression levels of Il1rl2, Rbck1, and Ppargc1a in tumor tissues of the CRC group and higher expression levels of Adipoq and Ucn in the colon of the control group." (PMID 36591255, 2022). "The same is true for immunohistochemical results, from which it can be concluded that silencing RBCK1 can inhibit tumor progression in ER-positive breast cancer cells under hypoxic conditions." (PMID 36473847, 2022). "RBCK1 was highly expressed in different cells in the tumor immune microenvironment (TIME), including CD4+ and CD8+ T cells, monocytes, macrophages, and NK cells." (PMID 34795663, 2021). "RBCK1 was co-localized with tumor-infiltrating immune cells according to the three single-cell RNA datasets." (PMID 34795663, 2021). "Using three scRNA-seq datasets, we detailed cell-type annotations at the single-cell level and focused on the tumor microenvironment of ccRCC to analyze the correlation between RBCK1 expression and immune abundance." (PMID 34795663, 2021). "In view of the findings of this study, future research directions can focus on the problem of RBCK1-regulated tumor microenvironment disorder mediating RCC malignant biological behavior." (PMID 34795663, 2021). "Consistent with the in vitro results, RBCK1 depletion significantly decreased the rate of tumor growth as compared with the control group (P < .05)." (PMID 30874541, 2019). "RBCK1 promotes tumor progression through several mechanisms." (PMID 35869046, 2022). "Furthermore, AIM2, CASP4, GSDMB, NOD2, and RBCK1 were also found to be highly expressed in ccRCC cell lines and tumor tissues, and GASP4 and GSDMB promote ccRCC cells’ proliferation, migration, and invasion." (PMID 36248876, 2022). "Various studies have shown that RBCK1 may affect the tumor microenvironment by enriching CAF, adipocytes, endothelial cells, TAM, etc., thereby exerting its carcinogenic role." (PMID 36473847, 2022).
tumor (continued). "The large-scale pan-cancer analysis also showed that RBCK1 had a strong prognostic value related to the significant differential expression of mRNAs between cancer and normal tissues and was correlated with tumor-infiltrating immune cells, tumor purity, and immune microenvironment scores." (PMID 34795663, 2021). "This suggested that RBCK1 expression is correlated with tumor-infiltrating immune cells." (PMID 34795663, 2021). "Therefore, we hypothesize that RBCK1 promotes tumor progression in ER-positive breast cancer by the HIF1α pathway." (PMID 36473847, 2022). "This may be the first study to show the tumor suppressive effect of RBCK1 in cancer progression." (PMID 36280829, 2022). "We also assessed whether RBCK1 affects tumor formation in vivo." (PMID 30874541, 2019). "We found that RBCK1 facilitated HCC progression by affecting microvascular invasion, cell migration, and apoptosis, revealing its potential role in tumor immunology and promising value as a prognostic biomarker and therapeutic target for HCC." (PMID 38214606, 2024). "Based on our expertise in ubiquitin ligases, we further investigated RBCK1 function in TNBC subtype, which revealed the tumor suppressor roles in TNBC through inhibition Hippo/YAP axis." (PMID 36280829, 2022). "Since the phenotype experiments have revealed that silencing RBCK1 can inhibit the migration, healing, colony formation, and lactate metabolism levels of T47D and MCF-7, we performed in vivo tumor growth experiments." (PMID 36473847, 2022). "Interestingly, RBCK1 showed significant differential expression between cancer and normal tissues and was significantly related to tumor-infiltrating immune cells, including tumor purity and immune checkpoint molecules such as PD-L1, CTLA-4, LAG-3, and TIGIT in ccRCC." (PMID 34795663, 2021). "In contrast, our transcriptome data revealed that HOIP (Rnf31), HOIL-1 (Rbck1), and Sharpin, components of LUBAC, were more highly expressed in LSCC compared with LADC tumor cells, which was confirmed by quantitative PCR (qPCR) and immunoblotting." (PMID 30642944, 2019). "In this study we extend these findings by demonstrating that the mRNA levels of RBCK1 and SHARPIN are also higher in tumors compared to adjacent non-tumor tissue in the same cross sectional study of samples (p < 0.001)." (PMID 29763465, 2018). "These correlations decreased for tumor tissues, as SHARPIN mRNA expression level was moderately correlated with RBCK1 and RNF31 mRNA expression levels (r = 0.52 and r = 0.48, respectively)." (PMID 29763465, 2018). "Regarding CNV analysis, we found that PANoptosis genes, especially NLRP3, RBCK1, PSTPIP2, and TNFAIP3, may promote tumor progression via CNV alteration." (PMID 36890219, 2023). "IHC staining validated that the protein levels of AIM2, CASP4, GSDMB, NOD2, and RBCK1 in tumor tissues were much higher than that in adjacent normal tissues." (PMID 36248876, 2022). "In this study we extend this observation by determining mRNA and protein expression levels of the two additional components of the LUBAC complex, RBCK1 and SHARPIN as well as RNF31 protein expression in the same cross sectional study of cancer tumors and adjacent non-tumor tissues." (PMID 29763465, 2018). "Since clinicopathological data for tumor samples including ERalpha, PR and HER2 protein expression and also clinical staging, histological grading, lymph node and menopausal statuses were available, we further examined the mRNA expression of RBCK1, RNF31 and SHARPIN in relation to these data." (PMID 29763465, 2018). "ROC Curve analysis revealed that up-regulated RNF31, RBCK1 and SHARPIN mRNA expression had high predictive abilities to distinguish tumor tissues from adjacent non-tumor tissues, with the Area Under the Curves (AUCs) being equal to 0.95, 0.94 and 0.91, respectively." (PMID 29763465, 2018).
cancer (14 papers, 2019 to 2025). A tumor composed of atypical neoplastic, often pleomorphic cells that invade other tissues. "Prior studies have implicated RBCK1 in chemotherapy resistance in colorectal, liver and ovarian cancers." (PMID 41031125, 2025). "Next, the correlation between genetic polymorphism of RBCK1 and cancer was studied by using cBioPortal database." (PMID 38214606, 2024). "The prognosis-associated PANoptosis-related genes (ZBP1, MAP3K7, and RBCK1) were highly elevated in the low-risk group and less expressed in the high-risk group, suggesting the participation of PANoptosis in cancer progression and as a potential target for therapeutic intervention in cancers." (PMID 38169587, 2024). "Among them, RBCK1 was associated with the highest number of cancer types." (PMID 36890219, 2023). "Although several studies implicated that RBCK1 could potentially been an oncogene, our understanding is that RBCK1 could act its roles in cancer type dependent manner." (PMID 36280829, 2022). "Our results show that the expression of RBCK1 is up-regulated in a variety of malignant tumors, and is closely related to the prognosis of patients." (PMID 38214606, 2024). "The purpose of this study is to find out the expression of RBCK1 in cancer, and to explore the relationship between RBCK1 and the prognosis of patients." (PMID 38214606, 2024). "For example, RBCK1 was highly upregulated in HNSC and LUSC and was associated with poor survival in these two cancer types." (PMID 36890219, 2023). "KEGG pathway analysis suggested that RBCK1 deletion influenced a variety of cancer-related pathways, including Hippo signal." (PMID 36280829, 2022). "Take these together, our results show that RBCK1 play a cancer-promoting role in HCC." (PMID 38214606, 2024). "We screened the expression of RBCK1 gene in a variety of cancers through TIMER2 database." (PMID 38214606, 2024). "Based on these studies, we conclude RBCK1 was mostly regarded as an oncogene in cancers." (PMID 36280829, 2022). "By single-cell analysis, we analyzed the expression of RBCK1 in pan-cancer tissues." (PMID 34795663, 2021). "Next, we analyzed the enrichment score of all TIME elements and RBCK1 in pan-cancers and found that the expression of RBCK1 was significantly correlated with increased numbers of immune cells, including B cells, Th2 cells, M1 macrophages, and the decreased numbers of CD4+ T cells and Treg cells." (PMID 34795663, 2021). "However, the function and mechanism of RBCK1 in pan-cancer and its association with immune cell infiltration have not been reported." (PMID 38214606, 2024). "Analysis of HCC and non-cancer specimens from TCGA and from our HCC sample bank revealed that both RNF31and RBCK1 are elevated in HCC tissues." (PMID 35869046, 2022). "To study the logical relationship between TNBC cancer phenotype and Hippo/YAP signal in RBCK1 function, we conducted several rescue assays." (PMID 36280829, 2022). "In addition, the survival analysis emphasized the prognostic significance of TRAFD1, SOD2, RIPK2, RBCK1, and MT2A as cancer-promoting factors in ccRCC and pRCC." (PMID 34795663, 2021).
infection (6 papers, 2015 to 2025). The state of being infected such as from the introduction of a foreign agent such as serum, vaccine, antigenic substance or organism. "In contrast, HOIL-1 knock-out (KO) mice, with null mutations in the Rbck1 gene that encodes HOIL-1, were resistant to infection with murine γ-herpesvirus 68 (MHV68) and Mycobacterium tuberculosis." (PMID 25599590, 2015).
myopathy (6 papers, 2015 to 2021). A disease of the muscle in which the muscle fibers do not function properly. "We can confirm the few previous reports insofar as both a myopathy and an immunological phenotype are part of the clinical spectrum of RBCK1-associated disease." (PMID 29260357, 2018). "A detailed review of the literature alongside with our newly reported cases shows that frameshift mutations beyond the N-terminus of RBCK1 may lead to a combined phenotype including both myopathy and immunological dysfunction in single families." (PMID 29260357, 2018). "Considering all cases reported to date, it appears that pathogenic RBCK1 variants appear to invariably cause a myopathy, but not necessarily immunological symptoms." (PMID 29260357, 2018). "Because Rbck1/HOIL‐1L deficiency leads to destabilization of other LUBAC components including HOIP and SHARPIN, the myopathy symptoms in these patients may derive from the deregulation of linear ubiquitination." (PMID 27702987, 2016).
digestive system tumors (1 paper, 2024). "The obtained data suggested that RBCK1 was expressed at higher levels in a wide array of tumors relative to normal tissues, especially digestive system tumors such as CHOL, COAD, LIHC, READ, STAD, and PAAD." (PMID 38214606, 2024).
metabolic disorders (1 paper, 2019). "We found that the depletion of RBCK1 expression caused an increase in the intracellular level of glucose, suggesting that RBCK1 may affect the efficiency of glucose utilization and decrease the glucose consumption that may eventually lead to metabolic disorders in RCC cells (P < .05)." (PMID 30874541, 2019).
RBCK1 also shares sentences with these, for which no sentence is quoted: dermatitis (6 papers); bacterial infections (3); dilated cardiomyopathy (2); inflammation (2); Listeria infection (2); lung carcinoma (2); Achalasia (1); atopic dermatitis (1); Atrophy (1); Autoimmunity (1); autoinflammatory syndrome (1); bladder cancer (1); cardiac hypertrophy (1); colitis (1); diffuse large B-cell lymphoma (1); Erythema (1); erythroderma (1); Failure to thrive (1); glioma (1); heart failure (1); helminth infection (1); herpesvirus infection (1); inflammatory bowel disease (1); inflammatory skin disease (1); influenza infection (1); intestinal inflammation (1); intraductal papillary mucinous neoplasms (1); kidney cancer (1); latent infection (1); liver cirrhosis (1).
A further 12 diseases each share a sentence with RBCK1 in 1 paper.